IL7 (interleukin 7)
Diseases named in the same sentence as IL7 in open-access papers (continued):
Sharing a sentence is not in itself a finding about the gene and the disease.
ulcerative colitis (6 papers, 2012 to 2024). An inflammatory bowel disease involving the mucosal surface of the large intestine and rectum. "It is implied that regulation of memory T cell differentiation through intervention with IL-7, IL-15, and IL-21 is an effective measure for the treatment of ulcerative colitis." (PMID 33597887, 2020). "Olsalazine significantly increased the contents of IL-2, IL-10, IL-22, TGF and EGF in ulcerative colitis rats, and significantly decreased the scores of DAI, CMDI, HS and the contents in IL-7, IL-17, TNF-α, IL-1β and IFN-γ when compared with the model group." (PMID 37610966, 2023). "It was suggested that olsalazine has a therapeutic effect on ulcerative colitis induced by DSS in mice, and the mechanism may be related to the increase of IL-2, IL-10, IL-22, TGF, and EGF and the decrease of the expression of IL-7, IL-17, TNF-α, IL-1β, and IFN-γ." (PMID 37610966, 2023).
cervical cancer (5 papers, 2015 to 2025). A primary or metastatic malignant neoplasm involving the cervix. "In cervical cancer, IL-7 levels were significantly elevated, especially in the invasive stages, indicating its potential involvement in tumor progression." (PMID 39334861, 2024). "In this context, our findings of lower risk of cervical cancer after PE suggest that immune regulation in these women, such as elevated TNF-α, IL-6, and IL-7 responses along with enhanced cytotoxic T-cell activation, might reduce the risk of persistent HPV infection." (PMID 40610749, 2025). "Furthermore, topical administration of IL-7-Fc in combination with the PHV vaccine increased a higher number of HPV-specific CD8+ T lymphocytes and exhibited a greater therapeutic effect against cervical cancer." (PMID 36389666, 2022).
co-infection (5 papers, 2015 to 2020). "Meanwhile, Tb co-infection is also associated with increased levels of plasma IL-7, which is essential in the establishment and maintenance of the HIV-1 reservoir." (PMID 33076959, 2020). "Tb co-infection has been shown to contribute to higher levels of systemic immune activation (marked by the increase of multiple pro-inflammatory bio-markers including IL-7) among PWH." (PMID 33076959, 2020). "In contrast, the HBV/HIV coinfection group has a different unique profile with GM-CSF-IL-4- IL-2-IFN-γ-IL12p70; and IL-7-IL-10 -IL1-β grouping together." (PMID 30815625, 2019). "To examine the immune profile of individuals with co-infection, we compared the concentration of 15 immune markers (IL-1β, IL-6, IL-8, TNF-α, IL-7, G-CSF, MCP-1/CCL2, MIP-1-α/CCL3, IL-12, IFN-γ, IL-13, IL-17A, GM-CSF, IL-10, and TGF-β1) among the three groups using Kruskal-Wallis ANOVA." (PMID 27128316, 2016). "To this end, we quantified the total HIV DNA, the level of plasma IL-7 concentration and the plasma IDO activities among PWH with or without Tb to determinate the impact of Tb co-infection on the size of the HIV reservoir." (PMID 33076959, 2020).
eosinophilia (5 papers, 2018 to 2022). "In contrast, the relative abundance of Moraxella and Streptococcus correlated positively with systemic and lower airway eosinophilia and bronchial pro-inflammatory cytokines including TNF and IL-7, respectively." (PMID 29885665, 2018).
fibrosis (5 papers, 2016 to 2024). the formation of excess fibrous connective tissue in an organ or tissue in a reparative or reactive process. "In BA patients, increased levels of IL-7, eotaxin, IP-10, and IL-13 were significantly associated with unfavorable outcomes including jaundice, fibrosis, and portal hypertension." (PMID 35452452, 2022). "On the one hand, it has been shown that serum IL-7 levels were negatively associated with fibrosis in NAFLD." (PMID 32168345, 2020). "Steatosis and fibrosis severity were associated with an increase in IL-8, fibrosis severity and portal inflammation were associated with an increase in soluble IL-2 receptor alpha, and fibrosis severity and portal inflammation were associated with a drop in IL-7." (PMID 38535313, 2024).
gastric cancer (5 papers, 2019 to 2024). A primary or metastatic malignant neoplasm involving the stomach. "There was significant difference in fold change in IL-7 concentration with respect to tumor location—the highest increase was observed in gastric cancers." (PMID 31185636, 2019). "However, the highest difference in IL-7 concentration between tumor and patient-matched normal tissue was in gastric cancer." (PMID 31185636, 2019). "We found that immune related genes such as TLR8, Interleukin-7 (IL-7), Leptin (LEP), IL1RN had intimate relationships with AQP9 expression in breast, colon, lung and gastric cancers." (PMID 33247170, 2020). "In the intestinal type and diffuse type of gastric cancer, the expression of 28 chemokines with their receptors such as CCL3 and CCL8 and 21 interleukins such as IL7 and IL16 demonstrated significantly statistical difference." (PMID 33426088, 2020). "For downstream inflammatory factors, our findings were supported by previous studies that demonstrated a strong association between pre-neoplastic alterations and the development of gastric cancer, involving various inflammatory regulators including bNGF, GCSF, IL-13, IL-5, IL-7, and MCSF." (PMID 39439893, 2024). "However, the role of IL-7 and CCR8 in gastric cancer development has not yet been clarified." (PMID 33816214, 2020).
sarcopenia (5 papers, 2023 to 2025). Progressive decline in muscle mass due to aging which results in decreased functional capacity of muscles. "Several inflammatory cytokines, such as CD6, HGF, and IL-7, have demonstrated suggestive associations with sarcopenia-related traits." (PMID 39193020, 2024). "Participants who met criteria for sarcopenia at baseline had significantly higher IL-7 concentration measured during the acute phase of illness (median 8.78pg/mL vs 6.52pg/mL; p=0.014)." (PMID 39012665, 2024). "Higher serum concentrations of IL-7 were measured during the acute phase of illness in participants who met criteria for sarcopenia at baseline." (PMID 39012665, 2024). "Participants with sarcopenia at baseline had higher IL-7 concentrations during acute phase of illness (median 8.78pg/mL vs 6.52pg/mL; p=0.014)." (PMID 39012665, 2024). "In this study, we employed MR analysis to provide a more holistic perspective on the causal relationship between inflammatory cytokines and sarcopenia, suggesting that elevated levels of IL-7, MCP-3, RANTES, and IL-1RA increase, whereas HGF, IP-10, and M-CSF decrease the risk of sarcopenia." (PMID 39345889, 2024).
T cell deficiency (5 papers, 2019 to 2026). "GX-I7 (rhIL-7-hyFc, efineptakin alfa) is a hybrid Fc-fused long-acting interleukin-7 (IL-7) with the aim of correcting T-cell deficiency, thereby strengthening the immune response to fight against cancer." (PMID 40490502, 2025). "The functions of (interleukin-7) IL-7 have also generated interest in its utilization to boost de novo T-cells formation following T-cells deficiency caused by HIV infection." (PMID 31487807, 2019).
type 2 diabetes (5 papers, 2015 to 2025). "In contrast, other studies have reported higher GCF levels of TNF-α and IL-7 in patients with type 2 diabetes than in systemically healthy individuals." (PMID 26211001, 2015). "Obese women with type 2 diabetes (T2D) and chronic inflammatory diseases are at higher risk of breast cancer, asT2D with obesity mediates the production of IL6, IL7, and CD68 macrophages, such as proinflammatory cytokines, which exacerbate the invasion of metastatic cancerous cells." (PMID 35401196, 2022).
acute GVHD (4 papers, 2012 to 2026). "Instead, low serum levels of IL-15 and interleukin-7 (IL-7), especially in the early post-transplant period, have been associated with a lower risk of acute GvHD (aGvHD) and a higher risk of relapse; thus supporting the role of these cytokines in improving T cell alloreactivity." (PMID 31881776, 2019). "Specifically, the 180-day cumulative incidence of grade II–IV acute GVHD was 29% in patients with day 7 IL-7 levels>median (5.1 pg/mL) versus 20% in patients with day 7 IL-7 levels ≤ median (P = 0.38)." (PMID 23437070, 2013). "TGF-β has been reported to restrain acute GVHD, while the response to IL-7 and IL-15 (in the lymphopenic setting induced during bone marrow transplantation) exacerbates GVHD." (PMID 22879925, 2012). "Similarly, the 180-day cumulative incidence of grade II–IV acute GVHD was 19% in patients with day 14 IL-7 levels>median (5.2 pg/mL) versus 37% in patients with day 14 IL-7 levels ≤ median (P = 0.18)." (PMID 23437070, 2013). "In the current study, we did not observe any association between levels of IL-7 or IL-15 early after allo-HSCT and grade II–IV acute GVHD." (PMID 23437070, 2013). "In summary, these data suggest that IL-7 and IL-15 levels remain relatively low after nonmyeloablative transplantation, and that IL-7 and IL-15 levels early after nonmyeloablative transplantation do not predict for acute GVHD." (PMID 23437070, 2013). "Importantly, IL-7 and IL-15 levels on days 7 or 14 after transplantation did not predict grade II–IV acute GVHD." (PMID 23437070, 2013).
allergic asthma (4 papers, 2018 to 2025). A asthma with a basis in a pathological type I hypersensitivity reaction. "In ovalbumin-induced allergic asthma mouse models, IL-7 signaling has been shown to be necessary for the survival of allergen-specific CD4 + T cells." (PMID 39806440, 2025). "TSLP, an interleukin-7 (IL-7)-like cytokine derived from epithelial cells, is considered as a master switch in Th2 mediated immune responses, and is believed to play a key role in allergic asthma." (PMID 30254626, 2018). "Considering the effects of IL-7 and IFNγ, and that the hippocampus is a major neurogenic niche in the developing brain, future studies may benefit from investigating the potential for hippocampal overgrowth in offspring brains in response to UIS or allergic asthma inflammation during pregnancy." (PMID 37919762, 2023).
anorexia nervosa (4 papers, 2016 to 2025). A disorder most often seen in adolescent females characterized by a refusal to maintain a minimally normal body weight, an intense fear of gaining weight, a disturbance in body image, and, in postmenarcheal females, the development of amenorrhea. "Interleukin (IL)−6 and IL-15 are higher, and IL-7 lower, in anorexia nervosa (AN) compared with controls." (PMID 41034374, 2025). "Low IL-7 is part of the adaptive profile in restrictive-type anorexia nervosa, confirming its difference with constitutional thinness." (PMID 27611669, 2016). "Therefore we evaluated circadian plasma levels of IL-7 in anorexia nervosa compared to constitutional thinness, healthy obese and control females." (PMID 27611669, 2016). "Results reveal elevations in interleukin (IL)-6 and IL-15 and reductions in IL-7 in people with anorexia nervosa in comparison to healthy controls, and no elevations in pro-inflammatory cytokines in people with bulimia nervosa." (PMID 41034374, 2025). "Plasma level of IL-7 is low in anorexia nervosa suggesting that IL-7 has no role in resistance to orexigenic signal but is another peptide taking part of the adaptive orexigenic profile in order to counteract the food restriction." (PMID 27611669, 2016).
Chagas disease (4 papers, 2017 to 2021). A parasitic infection caused by Trypanosoma cruzi. "In summary, the restriction of B cell development during experimental Chagas disease was accompanied by a loss in stromal cell integrity and reduction of stromal cell-derived IL-3, GM-CSF, and IL-7 and a reduction of SCF expression on stromal surface." (PMID 30619242, 2018). "Some of these differentially expressed genes were previously associated to Chagas disease (eg, IL7, CCR7, CCL19, GATA4, HLA-DPB1)." (PMID 28575239, 2017). "In chronic Chagas disease, Trypanosoma cruzi-specific T-cell function decreases over time, and alterations in the homeostatic IL-7/IL-7R axis are evident, consistent with a process of immune exhaustion." (PMID 34061845, 2021). "Impaired T-cell responses in chronic Chagas disease are specific for T. cruzi, but these alterations in the IL-7/IL-7R pathway are another example of how this chronic infection affects the general status of the host immune system." (PMID 30517089, 2018). "Increased serum levels of IL-7 in patients with less severe forms of Chagas disease may be induced by the need to maintain T cells during chronic infection because receptor-mediated uptake largely regulates IL-7 levels." (PMID 30517089, 2018). "Taken together, the present study demonstrated that defective signaling and regulatory mechanisms in the IL-7/IL-7R axis during the chronic phase of Chagas disease may affect the maintenance of parasite-specific IFN-γ-producing cells." (PMID 30517089, 2018).
chronic kidney disease (4 papers, 2012 to 2021). Impairment of the renal function secondary to chronic kidney damage persisting for three or more months. "CsA treatment decreases the immune system, specially T-cells number and activation, but alternatively the remaining immune cells can counterwork the immunologic depression by increasing IL-7 levels which could be correlated with the progression of chronic kidney disease in this study." (PMID 24971338, 2014). "The reasons for premature T cell ageing in patients with chronic renal failure are not known but a relative lack of the T cell growth factor IL-7 has been documented and may be important." (PMID 22971545, 2012).
Hodgkins lymphoma (4 papers, 2016 to 2022). A heterogeneous group of malignant lymphoid neoplasms of B-cell origin characterized histologically by the presence of Hodgkin and Reed-Sternberg (HRS) cells in the vast majority of cases. "For example, compared with healthy individuals, patients with Hodgkin’s lymphoma display higher serum levels of IL-7, and IL-7 mRNA-specific signals are detectable in tumor tissues." (PMID 34925323, 2021). "In addition, IL-7 signaling is suggested to be involved in chronic lymphoid leukemia (CLL) and Hodgkin’s lymphoma, and stimulation of CLL cells with IL-7 resulted in increased proliferation in vitro." (PMID 34066732, 2021).
Hyperglycemia (4 papers, 2017 to 2023). An increased concentration of glucose in the blood. "During hyperglycemia, sCD127 is glycated making it inaccessible to IL-7 and ineffective as an inhibitor of IL-7 signaling." (PMID 33301420, 2021). "This was thought to be mediated in part by increased glycosylation of sCD127 during hyperglycemia, impairing the ability of sCD127 to inhibit IL-7 activity." (PMID 29261677, 2017). "It is worth noting that hyperglycemia resulted in a glycosylated form of sCD127 that was ineffective as an IL-7 antagonist and glycosylated sCD127 was found in patients with T1DM, which provided new evidence that hyperglycemia regulates the immune network by acting on immune molecules." (PMID 31849842, 2019). "In addition, the higher levels of IL‐7 and IL‐8 in patients with DM may lead to more granulocyte infiltration, and these byproducts of hyperglycemia combined with oxidative stress can induce a proinflammatory response, which can lead to more severe inflammation and TB." (PMID 37434342, 2023).
lymphoproliferative disorders (4 papers, 2005 to 2023). "Additionally, IL-7 has been associated with lymphoproliferative disorders to which RA patients are already predisposed." (PMID 15642146, 2005). "Increased γc expression inhibited IL-7 signaling and rescued lymphoproliferative disorder in an IL-7Tg animal model, providing novel insights into T cell homeostasis." (PMID 37904191, 2023). "It is interesting to speculate on whether sγc overexpression would ameliorate the development of IL-7-mediated lymphoproliferative disorders (LPDs) through the dampening of IL-7 signaling." (PMID 30373315, 2018). "Since we recently found that a soluble form of the common γ-chain (γc) cytokine receptor (sγc) antagonistically regulates IL-7 signaling, IL-7 and sγc double-Tg mice were generated to investigate the effects of sγc overexpression in IL-7-mediated lymphoproliferative disorders (LPDs)." (PMID 30373315, 2018). "Correspondingly, IL7R−/− mice do not respond to IL7 and have severely reduced B- and T-cell counts; whereas, transgenic IL7-overexpressing mice develop lymphoproliferative disorders of B- and T-cell compartments." (PMID 29977016, 2019).
metastatic disease (4 papers, 2017 to 2023). "Although CRC patients indicated increased IL-7 levels than the controls, and the expression was associated with metastatic disease and tumor location, little is known about the fundamental causes of IL-7-induced CRC aggression." (PMID 38096329, 2023). "In summary, our study is the first to demonstrate IL-7 elevation in CRC in association with metastatic disease and tumor location." (PMID 27866242, 2017). "Nevertheless, there is a growing body of evidence linking IL-7/IL-7R signaling with tumor aggressiveness, metastatic disease, and unfavorable prognosis." (PMID 27866242, 2017). "Although IL-7 was detected to be elevated in CRC patients compared with the control group and the expression level was associated with metastatic disease and tumour location 49, 50, little progress has been made on the underlying mechanisms of IL-7-induced aggressiveness of CRC." (PMID 32760201, 2020).
Miscarriage (4 papers, 2020 to 2023). A pregnancy that ends at a stage in which the fetus is incapable of surviving on its own, defined as the spontaneous loss of a fetus before the 22th week of pregnancy. "Due to the increase in the ratio of Th17/Treg cells, IL-2 has also been linked to preeclampsia, miscarriage, and the IL-7/IL-7R signaling pathway in fetal miscarriage." (PMID 38131979, 2023). "Significantly elevated expressions of IL-7 in the decidua of women with spontaneous abortion and RPL indicate that IL-7 likely plays a significant role in promoting pro-inflammatory immune response at the embryo-maternal interface." (PMID 36613575, 2022). "Interestingly, the IL-7/IL-7R pathway which was reported functional on up-regulating Th17 immunity is also able to downregulate Treg immunity in recurrent spontaneous abortion." (PMID 35757768, 2022). "This might play an important role in pregnancy as IL-2 has been implicated to be upregulated in pre-eclampsia and miscarriage and IL-7/IL-7R signaling pathway in fetal miscarriage, due to the upregulation in the ratio of Th17/Treg cells." (PMID 32733490, 2020).
myocardial infarction (4 papers, 2019 to 2023). Gross necrosis of the myocardium, as a result of interruption of the blood supply to the area, as in coronary thrombosis. "Others suggested IL-7 to have predictive value for mortality from cardiogenic shock following myocardial infarction." (PMID 33985567, 2021). "Cagnin and Damas reported that IL-7 was upregulated in patients with cardiovascular atherosclerosis (particularly among patients with acute myocardial infarction and angina pectoris) compared with controls." (PMID 31164999, 2019). "Importantly, IL‐7 was detected in intestinal I/R in vitro and in vivo 38 and was identified as an expansion and activation driver of CD4 + CD28null T cells in myocardial infarction patients." (PMID 34581005, 2021).